MAGEA9B (MAGE family member A9B)
Description:
Not known, though may play a role in embryonal development and tumor transformation or aspects of tumor progression.
Gene: Protein-coding gene on chromosome X (149,581,653 to 149,587,459, reverse strand). Ensembl gene ENSG00000267978.
Subcellular location (Human Protein Atlas): Golgi apparatus; Nucleoplasm
Gene Ontology:
Molecular function: protein binding; histone deacetylase binding
Biological process: negative regulation of transcription by RNA polymerase II
Cellular component: nucleus
Homologues: Orthologues: macaque MAGEA9 (90% identical), zebrafish ndnl2 (21% identical), Drosophila melanogaster MAGE (17% identical). Paralogues in human: MAGEA9 (100% identical), MAGEA8 (67% identical), MAGEA4 (65% identical), MAGEA1 (61% identical), MAGEA11 (60% identical), MAGEA3 (59% identical), MAGEA12 (59% identical), MAGEA2 (59% identical), MAGEA2B (59% identical), MAGEA6 (58% identical), MAGEA10 (53% identical), MAGEB16 (47% identical), and 25 more.
Diseases named in the same sentence as MAGEA9B in open-access papers:
MAGEA9B is named in the same sentence as 6 diseases in open-access papers, as found by Europe PMC text mining. Sharing a sentence is not in itself a finding about the gene and the disease. The quoted sentences say what the papers report.
neuroblastoma (1 paper, 2014). Neuroblastoma (NB) is the most common solid, extracranial childhood tumor. "Importantly, MAGEA9B gene expression was also a significant (P = 0.014) marker of 5-year survival of neuroblastoma patients (GSE16237)." (PMID 25522241, 2014). "Additionally, MAGEA9B, along with two other targets of HOXD-AS1 - TNF and CNR1, were recently found to be a part of neuroblastoma signature identified in several datasets." (PMID 25522241, 2014).
cancer (3 papers, 2012 to 2025). A tumor composed of atypical neoplastic, often pleomorphic cells that invade other tissues. "We have excluded the least cancer-associated CTA genes: Magea12, Magea9b, Oip5 and Casc5." (PMID 41009820, 2025). "Out of these, FMR1NB, CTAG1A and MAGEA9B are cancer/testis antigens." (PMID 25884295, 2015).
tumor (2 papers, 2012 to 2025). "Genes involving the extracellular space and plasma membrane regulators were increased in aggressive MSI‐H CRC tumors, and tumor antigens (MAGEA3, MAGEA6, MAGEA9B, or MAGEC2) involving in the transcriptional and post‐translational regulations were represented in the aggressive MSI‐H signature." (PMID 39322998, 2025).
MAGEA9B also shares sentences with these, for which no sentence is quoted: gastric cancer (1 paper); head and neck squamous cell carcinoma (1); Lung squamous cell carcinoma (1).